DPP4 (dipeptidyl peptidase 4)
Diseases named in the same sentence as DPP4 in open-access papers (continued):
Sharing a sentence is not in itself a finding about the gene and the disease.
colitis (14 papers, 2016 to 2024). Inflammation of the colon. "Impact of HFD on DSS‐induced colitis may be linked to intestinal dysbiosis and specific genes such as Abca8b, Ace2, Apoa1, Apoa4, Apoc3, Aspa, Dpp4, Maob, Slc34a2, Slc7a9, and Trpm6." (PMID 39479684, 2024). "Overall, the findings indicate that the impact of HFD on DSS‐induced colitis may be linked to intestinal dysbiosis and specific genes such as Abca8b, Ace2, Apoa1, Apoa4, Apoc3, Aspa, Dpp4, Maob, Slc34a2, Slc7a9, and Trpm6." (PMID 39479684, 2024). "They first adopted DSS administration to induce colitis in DPP-4-deficient mice and wildtype mice." (PMID 35050153, 2022). "A similar study found that GLP-1 was significantly increased in mice with DSS-induced colitis treated with DPP-4 inhibitors." (PMID 37554552, 2023). "DSS-induced colitis in mice was improved by administration of DPP4 inhibitor ER-319711, as demonstrated by less colon shortening and weight loss." (PMID 35309368, 2022). "The levels of VIP and IL-6 in the colon and brain tissues were also increased in DPP4-/- mice during the acute inflammation phase of colitis." (PMID 35309368, 2022). "In dextran sulfate sodium (DSS)-induced colitis, DPP4-/- mice showed increased CD8+ T cells and NKT cells in the spleen, as well as increased macrophage infiltration and enhanced expression of NF-κB p65 subunit in colon mucosa." (PMID 35309368, 2022). "A model of TNBS-induced colitis in DPP4-/- mice showed higher serum levels of neuropeptide Y (NPY), vasoactive intestinal peptide (VIP) and IL-6, which are all substrates of DPP4, compared to C57BL/6 mice." (PMID 35309368, 2022). "IL-10 in the brain was found to reduce in wild-type mice, but increase in DPP4-/- mice, suggesting a potential role of DPP4 in regulating neuroimmune response in colitis development." (PMID 35309368, 2022). "Conversely, DPP-4-deficient rats reveal an apparent diminished disease activity index (DAI) in the low-dose DSS-induced colitis, especially in 1% DSS-induced colitis." (PMID 29270177, 2017). "Due to the vital role of GLPs in intestinal healing and anti-inflammatory function, a sound understanding of the production, regulation, and function of GLPs and their degrading enzyme DPP-4 will facilitate the treatment of colitis." (PMID 29270177, 2017). "Anagliptin, a DPP-4 inhibitor, facilitated the restoration of mucosal damage in a model of experimental murine colitis." (PMID 29228568, 2017). "On the other hand, DPP-4, the incretin degrading endopeptidase, has been found to be reduced in tissue and plasma in active CD and further inhibition of DPP-4 accelerated mucosal healing in a murine model of colitis." (PMID 27148273, 2016). "Additionally, a range of peptide DPP4 inhibitors have been confirmed to reduce colitis in mice through the same pathway, indicating that the overexpression of intestinal DPP4 is closely related to IBD." (PMID 39479684, 2024). "However, the effect of the DPP4 inhibitor on reducing the severity of colitis in HFD mice must be further confirmed." (PMID 39479684, 2024). "Inhibition of DPP4 activity using selective and nonselective inhibitors has been associated with improvements to disease severity in mouse models of colitis." (PMID 35060938, 2022). "Hence, DPP-4 involvement in the pathogenesis of colitis has been proposed." (PMID 29270177, 2017). "In IBD patients, DSS-induced colitis animal models, as well as DSS-treated Caco-2 cells, the cell surface expression and activity of various intestinal hydrolases such as SI and DPP4 is altered." (PMID 33572926, 2021). "A similar effect was also investigated in DPP-4 inhibitor anagliptin- and ER-319711-treated mice with DSS-induced colitis." (PMID 29270177, 2017). "At present, DPP-4 inhibitors are used to treat experimental mice colitis (DSS-induced mice colitis and TNBS-induced mice colitis), and their mechanism may be inhibiting IL-6 and TNF-α." (PMID 37554552, 2023).
colitis (continued). "While systemic and topical DPP-4 inhibitors reduce colitis severity and promote healing of colitis, Dpp4 KO does not protect from colitis but increases colonic myeloperoxidase activity and nuclear factor κbp65 subunit and modifies leucocyte trafficking." (PMID 30186247, 2018). "Furthermore, in DSS-induced colitis, a considerable increase of GLP-1 was detected in colitic mice with DPP-4 inhibitor treatment." (PMID 29270177, 2017).
fibrosis (14 papers, 2010 to 2025). the formation of excess fibrous connective tissue in an organ or tissue in a reparative or reactive process. "In our swine model, DPP-4 inhibitor treatment was associated with significant decreases in both interstitial fibrosis and perivascular fibrosis on Masson’s trichrome stain." (PMID 39074126, 2024). "Both DPP-4 knockout and DPP-4 inhibitor treatment in the CCl4-induced fibrosis model causes less intrahepatic crosslinked collagen accumulation and bridging fibrosis compared with control mice." (PMID 35163991, 2022). "Compared to limited cutaneous SSc, the soluble DPP4 levels further reduced in diffuse cutaneous SSc, which supports the hypothesis that DPP4 activity is associated with fibrosis progress in SSc." (PMID 35309368, 2022). "Collectively, these results demonstrate that microbiota-derived DPP4 exacerbates intestinal fibrosis in the DSS-induced chronic colitis model." (PMID 41334589, 2025). "Another consideration is that specific DPP4 inhibition has been shown to decrease liver fibrosis and slow HCC progression." (PMID 34771657, 2021). "Previous data showed that long-term DPP4 inhibition promoted cardiac fibrosis, inflammation, and reduced ventricular function in older diabetic mice." (PMID 29556215, 2018). "Importantly, aortic fibrosis and increased medial thickness were prevented with DPP-4 inhibition." (PMID 27391040, 2016).
lymphoma (14 papers, 2009 to 2024). A malignant (clonal) proliferation of B- lymphocytes or T- lymphocytes which involves the lymph nodes, bone marrow and/or extranodal sites. "In tumors, such as astrocytoma, gastrointestinal stromal tumors, and some lymphomas, higher expression of DPP4 is linked with tumor aggressiveness." (PMID 32498358, 2020).
psoriasis (14 papers, 2014 to 2025). An autoimmune condition characterized by red, well-delineated plaques with silvery scales that are usually on the extensor surfaces and scalp. "This also implies that at least one DPP-4 inhibitors and at least one monoclonal antibody for psoriasis were available in all markets." (PMID 36451186, 2022). "DPP4 expression is ubiquitous in the dermis, and the inhibition of DPP4 contributes to several cutaneous conditions, such as psoriasis, atopic dermatitis, cutaneous T‐cell lymphoma and keloids, amongst others." (PMID 36468400, 2022). "The expression of the DPP-4/CD26 protein is increased in several skin diseases, including such as T-cell lymphomas, psoriasis, lichen planus and atopic dermatitis." (PMID 31275298, 2019). "This is the first randomised clinical trial assessing dipeptidyl peptidase-4 inhibition therapy in psoriasis." (PMID 26767505, 2016). "This dual pattern is also observed in psoriasis, where serum DPP4 levels are decreased, whereas skin expression is elevated, suggesting that systemic and tissue-specific DPP4 dynamics may diverge in inflammatory skin diseases." (PMID 41373842, 2025). "In addition, DPP4 inhibition was also reported to improve psoriasis, probably by inhibiting T cell activation." (PMID 35309368, 2022). "Dipeptidyl peptidase-4 is expressed on keratinocytes and its activity is upregulated in psoriasis." (PMID 26767505, 2016). "One hypothesis of sitagliptin’s potential effect in psoriasis treatment is that inhibition of DPP-4 may inhibit T cell activation and improve psoriasis." (PMID 26767505, 2016). "Two cases of DPP-4 inhibitor therapy improving psoriasis severity have been reported." (PMID 26767505, 2016). "Dipeptidyl peptidase-4 inhibitors, which reduce systemic inflammation and improve metabolic health, may improve psoriasis severity and may also provide an opportunity to treat, and prevent, major comorbidities." (PMID 26767505, 2016). "In addition, sudden cession of drugs, stress event, dipeptidyl peptidase-4 inhibitor, and ulcerative colitis could also be possible triggers leading to pemphigoid in psoriasis patients." (PMID 35317170, 2022). "Several pieces of research showed that anti-hyperglycaemic agents, such as GLP-1 receptor agonist, DPP-4 inhibitors, and thiazolidinendiones, exert anti-psoriasis effects independent of weight loss and glycemic control by targeting keratinocyte proliferation and skin inflammation." (PMID 31540048, 2019). "Finally, zebrafish and human 3D organotypic models of psoriasis reveal the relevance of diabetic comorbidity in skin inflammation and suggest a therapeutic benefit of inhibiting GLUT1 and DPP4." (PMID 36076906, 2022). "The high concentration of DPP-4 expressed on keratinocytes and the fact that DPP-4 inhibition suppresses keratinocyte proliferation in vitro, and restores partially keratinocyte differentiation in vivo, support a potential role for DPP-4 inhibition therapy in the treatment of psoriasis." (PMID 26767505, 2016).
systemic sclerosis (14 papers, 2020 to 2025). A chronic disorder, possibly autoimmune, marked by excessive production of collagen which results in hardening and thickening of body tissues. "The related gene, DPP4, coding for dipeptidylpeptidase-IV was upregulated 6–11-fold on day 3 in the three strains and has been associated with organ fibrosis and systemic sclerosis." (PMID 33681189, 2021). "DPP4 was identified as a marker for activated fibroblasts in systemic sclerosis, and inhibition of DPP4 limits ECM deposition and fibrosis in heart, lungs, liver and kidneys, suggesting an active contribution to fibrosis." (PMID 40780446, 2025). "Another study indicated that DPP-4 is a marker of activated fibroblasts, and in a model of systemic sclerosis (a fibrotic disease), DPP-4 inhibitors exhibited significant anti-fibrotic effects." (PMID 41018201, 2025). "This aligns with studies in systemic sclerosis that identify DPP4 as a marker of activated dermal fibroblasts, suggesting conserved fibrogenic mechanisms across tissues." (PMID 41334589, 2025). "Another study suggested that the expression of DPP4 in the skin fibroblast was upregulated in patients with systemic sclerosis compared with that of healthy individuals." (PMID 35309368, 2022). "DPP4 has been demonstrated to define fibroblast populations in human skin biopsies of systemic sclerosis." (PMID 33117158, 2020). "Increased DPP4 levels were observed in fibroblasts isolated from individuals with systemic sclerosis relative to fibroblasts isolated from healthy individuals." (PMID 33117158, 2020). "Dpp4 is known play a role in fibrosis, having been described as a marker for pro-fibrotic dermal fibroblasts both in the setting of dermal scarring and in patients with systemic sclerosis." (PMID 39056733, 2024). "In addition, DPP4 is highly expressed on the surface of fibroblasts where it promotes the transition to myofibroblasts, and is considered one of the markers of activated fibroblasts in systemic sclerosis." (PMID 40780446, 2025). "Previous studies have shown that compared with normal controls, patients with RA, systemic lupus erythematosus, systemic sclerosis and IBD have decreased levels of serum DPP4." (PMID 38982370, 2024).
cognitive decline (13 papers, 2015 to 2025). "This supports existing literature that DPP4 inhibitors may be useful in combatting cognitive decline and offers a specific human pathology for future application." (PMID 37280551, 2023). "DPP4 inhibitors also have been reported to protect against cognitive decline in diabetic patients." (PMID 35601622, 2022). "Dipeptidyl peptidase 4 (DPP4) is a multifunctional exopeptidase that plays a key role in GLP-1 degradation, inflammation, and oxidative stress responses, which are closely associated with the onset of cognitive decline." (PMID 35646138, 2022). "Preclinical studies have suggested the potential role of newer glucose-lowering drugs, including dipeptidyl peptidase (DPP-4) inhibitors, GLP-1 RAs and sodium glucose co-transporter-2 (SGLT-2) inhibitors in protecting humans against cognitive decline." (PMID 37445790, 2023).
ischemia (13 papers, 2011 to 2022). A hypoperfusion of the BLOOD through an organ or tissue caused by a PATHOLOGIC CONSTRICTION or obstruction of its BLOOD VESSELS, or an absence of BLOOD CIRCULATION. "Ischemia induces loss of coronary microvascular endothelial DPP4 expression and increased Tissue Factor expression in AMI as well as in vitro in HUVECs." (PMID 23853775, 2013). "The first two sub-studies herein described reported the findings of fairly large comparisons of different DPP-4 inhibitors when directly perfused to beating mouse hearts subjected to ischemia reperfusion." (PMID 32796688, 2020). "This suggests that DPP-4 i diminished total monocyte/macrophages accumulation in the ischemia-injured tissue, and converted them into the M2 population, which displays strong anti-inflammatory, reparative and angiogenic functions." (PMID 30889182, 2019). "Inflamation caused a five-fold increase in DPP4 protein level suggesting a very potent posttranscriptional control of DPP4 expression during quickly developing inflammation and ischemia in neurons and glia." (PMID 29472575, 2018). "Our results are consistent with those of previous studies that demonstrated cardiac protection against ischemia-related myocardial injury through genetic deletion of DPP4." (PMID 25496837, 2014). "For example, it is well established that GLP-1R agonists and dipeptidyl peptidase-4 (DPP-4) inhibitors, which increase endogenous GLP-1, reduce infarct size after experimental ischaemia and enhance functional recovery upon reperfusion." (PMID 25725809, 2015). "Moreover, the dipeptidyl peptidase 4 (DPP-4)/GLP-1 axis can prevent vascular aging and maintain ischemia-induced neovascularization in mice." (PMID 35371594, 2022). "The finding coincides with the other study that direct infusion of DPP4 inhibitor before ischemia did not improve functional recovery after I/R injury in the isolated heart, suggesting that acute reduction of cardiac DPP4 activity is not sufficient to produce cardioprotection." (PMID 23359639, 2013).
lung adenocarcinoma (13 papers, 2014 to 2025). A carcinoma that arises from the lung and is characterized by the presence of malignant glandular epithelial cells. "Nevertheless, inhibition of CD26/DPP4 suppressed growth in human lung adenocarcinoma cell line by enhancing pro-inflammatory activity of macrophages and NK cell cytotoxicity." (PMID 40175622, 2025). "DPP4 expression was also analyzed using the Lung Adenocarcinoma dataset, which was last updated in 2018 and accessed via cBioPortal, referred to as The Cancer Genome Atlas." (PMID 41283988, 2025). "Moreover, we identified a positive correlation between fatty acid metabolism and DPP4 expression in The Cancer Genome Atlas Lung Adenocarcinoma (TCGA‐LUAD) dataset." (PMID 40479551, 2025). "DPP4 is shown to promote tumor metastasis in lung adenocarcinoma." (PMID 38890707, 2024). "None were treated with dipeptidyl peptidase-4 inhibitor (DPP4i).The seventh patient in the series had BP secondary to pembrolizumab treatment due to lung adenocarcinoma, which was crucial and could not be ceased." (PMID 37180101, 2023).
nasopharyngitis (13 papers, 2008 to 2025). An inflammatory process that affects the nasopharynx. "However, current DPP-4 inhibitors have been linked to adverse effects such as gastrointestinal issues, severe joint pain, nasopharyngitis, hypersensitivity, and nausea." (PMID 40761758, 2025). "In a meta-analysis of safety and efficacy of incretin-based therapies, DPP4 inhibitor use was associated with an increased risk of infection with RR 1.2 (95% CI 1.0, 1.4) for nasopharyngitis and 1.5 (95% CI 1.0, 2.2) for urinary tract infection (UTI) compared to placebo or active comparators." (PMID 33261058, 2020). "Based on the immune mechanisms between AR and DPP-4 inhibitor, we hypothesized that some adverse events of nasopharyngitis caused by DPP-4 inhibitors may be related to AR attacks." (PMID 31013793, 2019). "Prior meta-analyses of published studies of DPP-4 inhibitors (including sitagliptin and vildagliptin) have reported an increased risk for infections overall and for specific infections (nasopharyngitis, upper respiratory tract infection, and urinary tract infection)." (PMID 20412573, 2010). "The most common catastrophic effects of current DPP4 inhibitors are upper respiratory tract infection, nasopharyngitis, headache and urinary tract infection." (PMID 36014373, 2022). "DPP-4 inhibitors reduce the postprandial glucose levels by inhibiting DPP-4, and have numerous side effects, including hypersensitivity, nasopharyngitis, and headache." (PMID 32847055, 2020). "In contrast, DPP-4 inhibitors are taken orally, increase the half-life of endogenous GLP-1, are weight neutral, and are more commonly associated with nasopharyngitis." (PMID 22390369, 2012). "In contrast, the DPP-4 inhibitors are taken orally, increase the half-life of endogenous GLP-1, are weight neutral, and are more commonly associated with nasopharyngitis." (PMID 22390369, 2012). "DPP-4 inhibitors are conventional choices for diabetic treatment; however, side effects such as headache, bronchus infection, and nasopharyngitis might affect the daily lives of diabetic patients." (PMID 30691220, 2019). "However, current DPP-4 inhibitors may cause adverse effects, including gastrointestinal issues, severe joint pain (FDA safety warning), nasopharyngitis, hypersensitivity, and nausea." (PMID 40761758, 2025). "DPP-4 enzyme has been implicated to have a direct effect in T lymphocyte regulation, and DPP-4i suppress mitogen-stimulated T-cell responses, which leads to an increased incidence of infections (e.g., upper respiratory tract infection, nasopharyngitis, and urinary tract infection)." (PMID 32938499, 2020).
papillary thyroid carcinoma (13 papers, 2007 to 2026). "Through qRT-PCR experiments, it was confirmed that the expressions of TIMP1 and DPP4 were higher in thyroid papillary carcinoma than in normal PTC cells." (PMID 42073588, 2026). "FosB recruits KAT5 to potentiate proliferation and metastasis of papillary thyroid cancer cells via modulating DPP4 function." (PMID 35392432, 2022). "Ferroptosis regulator DPP4 was reported to activate the MAPK pathway in papillary thyroid carcinoma." (PMID 34291048, 2021). "DPP4 has been found to participate in thyroid papillary carcinoma cell proliferation by inhibiting the mitogen-activated protein kinase (MAPK) pathway." (PMID 34760708, 2021). "However, Hu X’s study showed the inhibited effect of DPP4 knockdown on the EMT of papillary thyroid carcinoma cells." (PMID 37907650, 2023). "Among various biomarkers, galectin-3 and dipeptidyl peptidase IV (DPP4) were found to be upregulated and consistently coexpressed in differentiated thyroid cancer." (PMID 34035807, 2021).